IFIT3 (interferon induced protein with tetratricopeptide repeats 3)
Diseases named in the same sentence as IFIT3 in open-access papers (continued):
Sharing a sentence is not in itself a finding about the gene and the disease.
COVID-19 (continued). "Additionally, elevated expression levels of IFIT3 and other ISGs, such as IFITM1, were observed in neutrophils from COVID-19 patients." (PMID 39664492, 2024). "In the gene expression validation experiment for the COVID-19 group, significant differences were viewed between the disease and normal groups for the IFIT3 and IFI27 genes, while no notable distinction was found in the EIF2AK2 gene." (PMID 38601162, 2024). "In line with the single-cell study, signs of an interferon response were observed irrespective of disease severity (IFIT1, IFIT3), while only severe COVID-19 patients’ granulocytes featured expression of genes with suppressive functionality, such as ARG1 or CD274 (PD-L1)." (PMID 33441124, 2021). "Moreover, it was found that increasing IFIT1 and IFIT3 has been reported previously in CD16+ monocytes of mild and severe COVID-19 patients, while the IRF7 was not differentially expressed." (PMID 35422859, 2022).
lupus (14 papers, 2008 to 2025). "Abnormal elevations in IFIT3 are associated with stimulants of interferon genes signaling in human systemic lupus erythematosus monocytes." (PMID 35627314, 2022). "Recent evidences have demonstrated that IFIT2 and IFIT3 may contribute to the pathogenesis of autoimmune diseases, such as systemic lupus erythematosus, sjögren’s syndrome and pemphigus." (PMID 32793290, 2020). "Research has shown that IFIT3 is significantly elevated in monocytes from systemic lupus erythematosus (SLE) patients, where it is positively correlated with cGAS-STING pathway activity, highlighting its role in amplifying antiviral responses." (PMID 40061935, 2025). "Lupus patients had low methylation and high expression of interferon regulatory genes, including BST2, IFIT3, IFI44L, and IFIT1." (PMID 38753689, 2024). "IFIT3 can be targeted to block type I IFN and inflammatory cytokine synthesis by cGAS/STING pathway in lupus affected individuals." (PMID 34079550, 2021). "In terms of epigenetics, IFI44 and IFIT3 were hypomethylated in comparisons between lupus patients and non-lupus subjects." (PMID 34760904, 2021). "In the present report, RhoA mRNA expression further is shown to be higher in the PBMCs of lupus patients when compared to healthy controls, and expression levels correlate positively with type I IFN scores and interferon-induced genes, including CXCL10, OAS1, IFIT3, and MX1." (PMID 38243295, 2024). "In our project,RhoA mRNA expression further has been shown to be higher in the PBMCs of lupus patients when compared to healthy controls, and expression levels correlate positively with type I IFN scores and interferon-induced genes, including CXCL10, OAS1, IFIT3 and MX1." (PMID 37790522, 2023). "A more attractive candidate is IFN induced protein with tetratricopeptide repeats 3 (IFIT3), which is highly up-regulated in SARS-CoV-2 infected bronchial epithelial cells: IFIT3 interacts with both STING and TANK-binding kinase 1 genes, and activate them in some disorders like lupus." (PMID 33335532, 2020).
influenza (12 papers, 2011 to 2025). An acute viral infection of the respiratory tract, occurring in isolated cases, in epidemics, or in pandemics; it is caused by serologically different strains of viruses (influenzaviruses) designated A, B, and C, has a 3-day incubation period, and usually lasts for 3 to 10 days. "Furthermore, this GO analysis indicated that genes associated with the antiviral response to influenza (e.g., Ifi27l2a, Isg20, Oas1a, Isg15, Ifit1, Oasl1, and Ifit3) were strongly enriched in mice vaccinated with WIV alone as compared with mice vaccinated with WT IL-1β or CD8α ALN-1." (PMID 32714571, 2020). "We also observed changes in the IFIT3 (Interferon-Induced Protein with Tetratricopeptide Repeats 3) gene involved in the antiviral innate immune response to respiratory viruses including influenza." (PMID 40916026, 2025). "Genes such as Irf7, Irf9, Mx1, Ifit3, Oas1a (L5) were induced most highly in lungs of virally infected mice (influenza and RSV)." (PMID 31253760, 2019). "Additionally, a signature associated with influenza (APOL6, IFIT3) was detected in the disease category." (PMID 40916026, 2025). "One group of ISGs, as represented by several well-known anti-influenza ISGs (Gbp3, Ifit3, Isg15, and Mx1/2), showed a kinetic pattern of mRNA expression largely resembling that of IFN-γ mRNA, suggesting that they were likely to be directly regulated by IFN-γ in an autocrine manner." (PMID 35296070, 2022). "IFIT1, IFIT3, IFITM3, MX1, and ISG15 have all been shown to possess anti-influenza activities; however, a genetic variant of IFITM3 has been associated with severe influenza infection and higher hospitalization rate." (PMID 33347425, 2020). "The influenza group’s validation experiment showed significant differences in all six genes (IFI44L, IFI44, RSAD2, IFIT3, EIF2AK2, and IFI27)." (PMID 38601162, 2024). "We next assessed expression levels of various cytokines and chemokines (i.e., IFNB1, IFNL1, IFNL2/3, IFIT1, IFIT3, OAS1, MX1, IL‐6, CXCL10, and IFITM1) which were triggered by influenza and OC43 virus infections alone or together by qPCR." (PMID 38556468, 2024).
breast carcinoma (11 papers, 2018 to 2025). "Our results suggest that when treated with xenogeneic RNA and INFα, the intensity of IFIT3 mRNA expression is inversely associated with the baseline level of this mRNA in breast cancer cells." (PMID 29986702, 2018). "IFIT3 expression was reported to be higher in the peripheral double-negative T cells (a distinct subset of T lymphocytes implicated in immune responses) of breast cancer patients compared to healthy controls." (PMID 40564154, 2025). "Conversely, hub genes such as H2BC11, MX1, OAS2, and IFIT3 displayed greater expression in more aggressive breast cancer subtypes." (PMID 41009689, 2025). "IFIT3-positive neutrophils, that appear to play a role in the formation and development of lung metastases in breast cancer, were, in mouse models, reported to be significantly abundant in the metastatic lung microenvironment as compared to primary tumor." (PMID 40564154, 2025). "We have identified four mouse myeloid subpopulations that highly correlate with breast cancer metastasis to lung, including Tppp3+ monocytes, Isg15+ macrophages, Ifit3+ neutrophils, and Il12b+ DCs." (PMID 37483625, 2023). "Our findings suggest that expression of IFIT3 mRNA can be used as a prognostic marker of breast cancer cell sensitivity to immunostimulating therapeutics." (PMID 29986702, 2018). "A recent study has identified a specific module with the highest correlation for each breast cancer subtype, where IFIT3 was a hub gene with the highest correlation for a Basal A subtype (that often includes the TNBC subtype) suggesting its potential importance in this subtype." (PMID 40564154, 2025). "Furthermore, higher expression of IFIT3 was correlated with better overall survival and immune infiltration in breast cancer patients." (PMID 40564154, 2025). "In breast cancer, IFIT3 might play an important role in modulation of the immune responses to cancer cells and treatment resistance." (PMID 40564154, 2025). "On the other hand, a pro-oncogenic role of IFIT3 in mouse breast cancer models has been reported." (PMID 40564154, 2025). "Recent studies of IFIT3 have highlighted its function as oncogene in various human cancers including breast cancer, pancreatic cancer, and liver cancer, and high expression of IFIT3 enhanced chemotherapy resistance of PDAC cells and was independently correlated to shorter patients’ survival." (PMID 38273364, 2024). "In addition, our analysis identified an IFN-responsive neutrophil population with high expression of IFN-responsive genes (Ifit3, Ifit1, Ifit3b, Ifi47, Ifitm3, Rsad2, Isg15, and Isg20), which is more present in metastatic lung of breast cancer." (PMID 37483625, 2023). "Recent studies have found that the protection mechanism of Ifit3 for the host is not only against viruses, but is also effective against tumors such as breast cancer, and oral squamous cell carcinoma, as well as bacteria and parasite infections such as pneumococcus, plasmodium." (PMID 32731337, 2020). "Accordingly, high IFIT1 and IFIT3 expression have been correlated with a better therapeutic response to IFNs along with chemotherapeutics and immunostimulating agents in patients with breast cancer, glioblastoma, and hepatocellular carcinoma." (PMID 31921891, 2019). "Previously, we analysed the influence of artificial small non-coding RNAs on gene expression in cancer cells and determined that transfection of MCF-7 breast cancer cells with artificial analogues of box C/D snoRNAs strongly induced activation of innate immunity genes, including IFIT3." (PMID 29986702, 2018). "It is known that the induction of IFN/STAT1-related gene expression, which includes IFIT3, could be an early predictive marker of tumour response to chemotherapy in ER− breast cancers." (PMID 29986702, 2018). "Thus, the role of IFIT3 in breast cancer might be multifaceted and requires further granular understanding." (PMID 40564154, 2025). "Thus, IFIT3 may serve as a favorable prognostic indicator in breast cancer." (PMID 40564154, 2025).
breast carcinoma (continued). "For instance, IFIT3 and IFI44 mRNA were highly expressed in the invasive human breast cancer cell line MDAMB231, while their expression was low in the non-invasive MDAMB453." (PMID 36882786, 2023). "IFIT1 and IFIT3 genes are classified as IRDS subset genes and are considered as predictive biomarkers for chemotherapy and radiation therapy in many primary human cancers, such as breast cancer, head and neck cancer, prostate cancer, lung cancer, and glioma." (PMID 31921891, 2019). "Interestingly, protein abundance of HPRT1, HNRNPA0, IFIT3, CTNND1 and EIF4A3 predicted poor overall survival in breast cancer patients, however, PPM1A association was non-significant." (PMID 32532008, 2020). "Obviously, proportions of ISG15+ macrophages and IFIT3+ neutrophils in primary tumor have low levels as that in normal lung but not TPPP3+ monocytes and IL12B+ DCs, which indicate that these myeloid subpopulations may have different degrees of association with breast cancer metastasis to lung." (PMID 37483625, 2023). "In indirect support of tumor suppressive roles of IFIT3 in breast cancer, it has been shown that non-malignant breast cells express relatively higher IFIT3 mRNA in culture conditions, compared to MCF7 and MDA-MB-231 breast cancer cell lines." (PMID 40564154, 2025).
hepatocellular carcinoma (10 papers, 2018 to 2024). A malignant tumor that arises from hepatocytes. "The HPA database indicated that UBE2O exhibited protein expression patterns opposite those of IFIT3 in both liver tissue and hepatocellular carcinoma tissue, although its expression was positively correlated with that of BST2 and TRIM21." (PMID 38129382, 2023). "In summary, UBE2O reduces the effectiveness of interferon-α by degrading IFIT3 in hepatocellular carcinoma." (PMID 38129382, 2023). "As an example, high expression of IFIT3 predict better response to IFN-α therapy in patients with hepatocellular carcinoma." (PMID 37980495, 2023). "Among the 10 GBP1-related proteins, IFIT3 is an interferon-induced protein, and high IFIT3 expression in hepatocellular carcinoma patients predicted a better response to IFN-α therapy." (PMID 35222540, 2022). "Recently, it was demonstrated that the level of expression of hepatic interferon-induced protein with tetratricopeptide repeats 3 (IFIT3) mRNA predicts the IFNα therapeutic response in patients with hepatocellular carcinoma." (PMID 29986702, 2018). "In hepatocellular carcinoma, IFIT3 could bind signal transducer and activator of transcription 1 (STAT1) and STAT2 to enhance STAT1–STAT2 heterodimerization and nuclear translocation upon IFN-α treatment, thus promoting IFN-α effector signalling." (PMID 34418997, 2021). "Previous studies have suggested that IFIT3 enhances the interferon (IFN) effector signaling pathway by promoting the formation and nuclear localization of the STAT1-STAT2 heterodimer in hepatocellular carcinoma." (PMID 39139574, 2024). "IFIT3 can promote IFN-α effector signaling, which in turn predicts IFN-α therapeutic response in patients with hepatocellular cancer." (PMID 35280763, 2022). "Yang studied the expression of IFIT3 in hepatocellular carcinoma specimens following IFN therapy and showed that the activation of IFIT3 expression correlates with patient survival." (PMID 29986702, 2018). "There was a negative correlation between UBE2O and IFIT3 protein expression in hepatocellular carcinoma patients." (PMID 38129382, 2023).
oral squamous cell carcinoma (10 papers, 2020 to 2025). "For example, overexpression of IFIT1 or IFIT3 increased oral squamous cell carcinoma (OSCC) resistance to multiple chemotherapeutic drugs, including 5FU, cisplatin, oxaliplatin, carboplatin." (PMID 37980495, 2023). "For example, induction of ISG15 or IFIT1 in human squamous cell carcinoma cancer cell line conferred doxorubicin chemo-resistance, or overexpression of IFIT1 and IFIT3 in oral squamous cell carcinoma (OSCC) promoted experimental metastasis." (PMID 35565392, 2022). "IFIT1 and IFIT3 contribute to the metastasis of oral squamous cell carcinoma, and serve as prognostic markers for patients with this disease." (PMID 35280763, 2022). "The study covering the role of IFIT1 and IFIT3 genes on drug resistance in OSCC cells (oral squamous cell carcinoma) showed that silencing of IFIT1 and IFIT3 by shRNA increased the sensitivity to cisplatin, thus further implicating their role in chemotherapy resistance." (PMID 33922087, 2021). "However, a prognostic significance in cancer has been suggested for IFITs and a novel role for IFIT1 and IFIT3 has been suggested in progression and metastasis in oral squamous cell carcinoma through interaction with annexin A2, which enhances recycling of the EGF receptor." (PMID 38447798, 2024). "In oral squamous cell carcinoma (OSCC), IFIT1 and IFIT3 promote metastasis, while IFIT2 exhibits the opposite effect." (PMID 36851555, 2023). "It has been reported that IFIT1 and IFIT3 are critical for EGFR recycling and activation in oral squamous cell carcinoma." (PMID 35280763, 2022). "In oral squamous cell carcinoma (OSCC), for instance, IFIT3 ectopic expression has been shown to correlate with poor survival in OSCC patients." (PMID 34622927, 2021).
pancreatic cancer (10 papers, 2014 to 2025). "The role of IFIT3 in cancer is not well understood but inflammation is linked to pancreatic cancer progression and treatment-resistant metastasis." (PMID 28356064, 2017). "IFIT3 is responsible for inflammatory stimulus in pancreatic cancer, but this gene may be associated with inflammation in BRCA." (PMID 31311202, 2019). "The role of IFIT3 in pancreatic cancer was corroborated in later in vitro studies, which showed that IFIT3 promotes metastasis." (PMID 36851555, 2023). "In the setting of pancreatic cancer, IFIT3 expression increases resistance against chemotherapy agents, such as gemcitabine and paclitaxel." (PMID 36851555, 2023). "Along with their role in OSCC, IFIT1 and IFIT3 have recently been shown to contribute to the progression of pancreatic cancer, which exhibits a 5-year overall survival rate of about 7%." (PMID 36851555, 2023). "We show that the increased expression of IFIT3 is in part responsible for the more aggressive phenotype seen in the pancreatic cancer cell line L3.6pl as compared to its parental line COLO357FG." (PMID 25650658, 2015). "The expression levels of IFIT3 in pancreatic cancer cells were alterable as expected by IFN treatment, and by inhibition of STAT1 and NFκB signaling." (PMID 25650658, 2015). "IFIT3, which is known to be upregulated during inflammation and cellular stress of different kinds, appears to play an important role in pancreatic cancer biology." (PMID 25650658, 2015). "Gene array data recently identified upregulation of interferon-induced protein with tetratricopeptide repeats 3 (IFIT3) in aggressive pancreatic cancer cells." (PMID 25650658, 2015). "Although not statistically significant, this data strongly suggests that further investigation of the potential role of IFIT3 in pancreatic cancer is warranted." (PMID 25650658, 2015). "Orthotopic injection of IFIT3 overexpressing pancreatic cancer cells led to the formation of tumors with greater mass and higher rates of metastasization." (PMID 25650658, 2015). "Upregulation of IFIT3 was confirmed in the aggressive pancreatic cancer cell line L3.6pl compared with its less aggressive cell line of origin, COLO357FG." (PMID 25650658, 2015). "This was supported by the observation that IFIT3 overexpression increases secretion of IL-6, which in turn favors pancreatic tumor growth and the maintenance of an inflammatory stimulus in the stromal tissue." (PMID 25650658, 2015). "However, the researchers found that pancreatic cancer patients who received neoadjuvant chemotherapy had a significantly longer DFS when IFIT3 expression in their tumors was low." (PMID 40564154, 2025). "Similar to IFIT1, IFIT3 also contributes to the progression of pancreatic cancer." (PMID 36851555, 2023). "IFIT3’s effect on chemotherapy treatment in pancreatic cancer is opposite to its effect in OSCC." (PMID 36851555, 2023). "Targeting IFIT3/VDAC2 may represent a novel strategy to sensitize aggressive forms of pancreatic cancer to conventional chemotherapy regimens." (PMID 32641986, 2020). "Targeting IFIT3/VDAC2 may represent a potential strategy to re-sensitize aggressive pancreatic cancer to conventional chemotherapy regimens." (PMID 32641986, 2020). "In the present study, we investigate the influence of IFIT3 on the malignant potential of pancreatic cancer cells, describe protein-protein interactions involving IFIT3 and elucidate possible mechanisms by which constitutive upregulation of IFIT3 is mediated in L3.6pl." (PMID 25650658, 2015). "IFIT3 appears to act as a pro-oncogene in some cancers, such as HNSCC/OSCC; pancreatic cancer and CRC (by promoting cell viability and migration)." (PMID 40564154, 2025). "Some of them (ITGA3, CDK1, IFIT3, ANXA1, ANXA2, OAS1, and LACTB) have been studied to varying degrees concerning their relationship with pancreatic cancer." (PMID 36834681, 2023).
pancreatic cancer (continued). "The PANCALYZE trail aims to predict the clinical course of pancreatic cancer on the basis of CXCR4, SMAD4, SOX9 and IFIT3 expression." (PMID 28356064, 2017). "The overexpression of the IFIT3 and IFI27 genes has been reported to induced tumour proliferation, angiogenesis and chemoresistance in pancreatic carcinoma cells." (PMID 24270600, 2014). "Unlike IFIT1, IFIT3 promotes metastasis in pancreatic cancer cells by inhibiting the proapoptotic effects of IFIT2 and by upregulating the secretion of vascular endothelial growth factor (VEGF) and IL-6." (PMID 36851555, 2023). "A retrospective study analyzing patient pancreatic cancer cells revealed that patients undergoing neoadjuvant therapy exhibited longer disease-free survival times if they had IFIT3-negative cancer cells." (PMID 36851555, 2023). "Analysis of this database showed that IFIT3 was detectable at the protein level by tissue microarray in 5 out of 11 pancreatic cancer samples while no expression was seen in normal pancreas." (PMID 25650658, 2015). "Despite still being alterable by “classical” IFN or NFκB signaling, our findings indicate upregulation of IFIT3 without an adequate inflammatory stimulus in the more aggressive pancreatic cancer cell line." (PMID 25650658, 2015). "In order to assess the biological influence of IFIT3 expression on the malignant potential of pancreatic cancer cells, COLO357FG cells and L3.6pl cells were stably transfected with either vectors resulting in over-expression of IFIT3 (CMV-IFIT3) or empty vectors as control (CMV-null) (bottom)." (PMID 25650658, 2015).